SIRT2 (sirtuin 2)
Description:
NAD-dependent protein deacetylase, which deacetylates internal lysines on histone and alpha-tubulin as well as many other proteins such as key transcription factors. Participates in the modulation of multiple and diverse biological processes such as cell cycle control, genomic integrity, microtubule dynamics, cell differentiation, metabolic networks, and autophagy. Plays a major role in the control of cell cycle progression and genomic stability. Functions in the antephase checkpoint preventing precocious mitotic entry in response to microtubule stress agents, and hence allowing proper inheritance of chromosomes. Positively regulates the anaphase promoting complex/cyclosome (APC/C) ubiquitin ligase complex activity by deacetylating CDC20 and FZR1, then allowing progression through mitosis. Associates both with chromatin at transcriptional start sites (TSSs) and enhancers of active genes. Plays a role in cell cycle and chromatin compaction through epigenetic modulation of the regulation of histone H4 'Lys-20' methylation (H4K20me1) during early mitosis. Specifically deacetylates histone H4 at 'Lys-16' (H4K16ac) between the G2/M transition and metaphase enabling H4K20me1 deposition by KMT5A leading to ulterior levels of H4K20me2 and H4K20me3 deposition throughout cell cycle, and mitotic S-phase progression. Deacetylates KMT5A modulating KMT5A chromatin localization during the mitotic stress response. Also deacetylates histone H3 at 'Lys-57' (H3K56ac) during the mitotic G2/M transition. Upon bacterium Listeria monocytogenes infection, deacetylates 'Lys-18' of histone H3 in a receptor tyrosine kinase MET- and PI3K/Akt-dependent manner, thereby inhibiting transcriptional activity and promoting late stages of listeria infection. During oocyte meiosis progression, may deacetylate histone H4 at 'Lys-16' (H4K16ac) and alpha-tubulin, regulating spindle assembly and chromosome alignment by influencing microtubule dynamics and kinetochore function. Deacetylates histone H4 at 'Lys-16' (H4K16ac) at the VEGFA promoter and thereby contributes to regulate expression of VEGFA, a key regulator of angiogenesis. Deacetylates alpha-tubulin at 'Lys-40' and hence controls neuronal motility, oligodendroglial cell arbor projection processes and proliferation of non-neuronal cells. Phosphorylation at Ser-368 by a G1/S-specific cyclin E-CDK2 complex inactivates SIRT2-mediated alpha-tubulin deacetylation, negatively regulating cell adhesion, cell migration and neurite outgrowth during neuronal differentiation. Deacetylates PARD3 and participates in the regulation of Schwann cell peripheral myelination formation during early postnatal development and during postinjury remyelination. Involved in several cellular metabolic pathways. Plays a role in the regulation of blood glucose homeostasis by deacetylating and stabilizing phosphoenolpyruvate carboxykinase PCK1 activity in response to low nutrient availability. Acts as a key regulator in the pentose phosphate pathway (PPP) by deacetylating and activating the glucose-6-phosphate G6PD enzyme, and therefore, stimulates the production of cytosolic NADPH to counteract oxidative damage. Maintains energy homeostasis in response to nutrient deprivation as well as energy expenditure by inhibiting adipogenesis and promoting lipolysis. Attenuates adipocyte differentiation by deacetylating and promoting FOXO1 interaction to PPARG and subsequent repression of PPARG-dependent transcriptional activity. Plays a role in the regulation of lysosome-mediated degradation of protein aggregates by autophagy in neuronal cells. Deacetylates FOXO1 in response to oxidative stress or serum deprivation, thereby negatively regulating FOXO1-mediated autophagy. Deacetylates a broad range of transcription factors and co-regulators regulating target gene expression. Deacetylates transcriptional factor FOXO3 stimulating the ubiquitin ligase SCF(SKP2)-mediated FOXO3 ubiquitination and degradation (By similarity). Deacetylates HIF1A and therefore promotes HIF1A degradation and inhibition of HIF1A transcriptional activity in tumor cells in response to hypoxia. Deacetylates RELA in the cytoplasm inhibiting NF-kappaB-dependent transcription activation upon TNF stimulation. Also deacetylates EIF5A. In addition to protein deacetylase activity, also acts as a protein-lysine deacylase by recognizing other acyl groups: catalyzes removal of N(6)-benzoyl (benzoyl) and N(6)-methacryl (methacryl) acyl groups from lysine residues, leading to histone debenzoylation and demethacrylation, respectively. Functions as a negative regulator on oxidative stress-tolerance in response to anoxia-reoxygenation conditions. Plays a role as tumor suppressor. In addition to protein deacetylase activity, also has activity toward long-chain fatty acyl groups and mediates protein-lysine demyristoylation and depalmitoylation of target proteins, such as ARF6 and KRAS, thereby regulating their association with membranes. [Isoform 1]: Deacetylates EP300, alpha-tubulin and histone H3 and H4. [Isoform 2]: Deacetylates EP300, alpha-tubulin and histone H3 and H4. [Isoform 5]: Lacks deacetylation activity, at least toward known SIRT2 targets.
Synonyms: SIR2L; SIR2L2; SIR2
Tractability: Small molecule: a structure with a bound ligand is known; a high-quality ligand is known; it has a high-quality binding pocket; it belongs to a druggable protein family. Antibody: its Gene Ontology location is reachable by antibodies, with high confidence. PROTAC: it is named in the literature on targeted protein degradation; UniProt records ubiquitination sites on it; ubiquitination databases record sites on it; its protein half-life has been measured; a small molecule that binds it is known.
Target class: Histone deacetylase; HDAC class III; Epigenetic regulator; Eraser
Safety:
Unwanted effects reported when the protein is acted on. In parentheses: how it was acted on, where the effect was seen, and who reports it.
hepatotoxicity (source: ClinPGx)
Gene: Protein-coding gene on chromosome 19 (38,878,555 to 38,900,501, reverse strand). Ensembl gene ENSG00000068903.
Subcellular location: Nucleus; Cytoplasm, perinuclear region; Cytoplasm; Cytoplasm, cytoskeleton; Cytoplasm, cytoskeleton, microtubule organizing center, centrosome; Cytoplasm, cytoskeleton, microtubule organizing center, centrosome, centriole; Cytoplasm, cytoskeleton, spindle; Midbody; Chromosome; Perikaryon; Cell projection; Cell projection, growth cone; Myelin membrane; Cytoplasm (Isoform 1); Cytoplasm (Isoform 2); Cytoplasm (Isoform 5)
Subcellular location (Human Protein Atlas): Cytosol; Nucleoli; Nucleoplasm; Plasma membrane
Pathways (Reactome):
Cell Cycle: Initiation of Nuclear Envelope (NE) Reformation
Gene Ontology:
Molecular function: chromatin binding; DNA-binding transcription factor binding; histone acetyltransferase binding; histone benzoyllysine debenzoylase activity; histone deacetylase activity; histone deacetylase activity, NAD-dependent; histone deacetylase binding; histone H4K16 deacetylase activity, NAD-dependent; histone methacryllysine demethacrylase activity; NAD+ binding; NAD+ poly-ADP-ribosyltransferase activity; NAD-dependent protein demyristoylase activity; NAD-dependent protein depalmitoylase activity; NAD-dependent protein lysine deacetylase activity; protein binding; protein lysine deacetylase activity; tubulin deacetylase activity; ubiquitin binding; zinc ion binding; NAD+-protein mono-ADP-ribosyltransferase activity; NAD binding; NAD-dependent protein lysine deacylase activity
Biological process: cellular response to hypoxia; epigenetic regulation of gene expression; negative regulation of autophagy; negative regulation of DNA-templated transcription; negative regulation of protein catabolic process; negative regulation of striated muscle tissue development; negative regulation of transcription by RNA polymerase II; peptidyl-lysine deacetylation; positive regulation of fatty acid biosynthetic process; positive regulation of proteasomal ubiquitin-dependent protein catabolic process; proteasome-mediated ubiquitin-dependent protein catabolic process; protein deacetylation; regulation of cell cycle; substantia nigra development; tubulin deacetylation; cellular response to caloric restriction; cellular response to epinephrine stimulus; cellular response to oxidative stress; heterochromatin formation; lipid catabolic process; mitotic nuclear membrane reassembly; myelination in peripheral nervous system; negative regulation of fat cell differentiation; negative regulation of oligodendrocyte progenitor proliferation; negative regulation of peptidyl-threonine phosphorylation; and 19 more
Cellular component: centriole; centrosome; chromosome; cytoplasm; cytosol; microtubule; midbody; mitochondrion; mitotic spindle; nucleolus; nucleoplasm; nucleus; spindle; chromatin silencing complex; glial cell projection; heterochromatin; juxtaparanode region of axon; lateral loop; meiotic spindle; myelin sheath; paranodal junction; paranode region of axon; perikaryon; perinuclear region of cytoplasm; Schmidt-Lanterman incisure; and 3 more
Genetic constraint (gnomAD): Loss-of-function variants: 43 observed, 53.72 expected, observed/expected ratio (o/e) 0.8, 90% interval 0.63 to 1.03. The upper end of that interval is the gene's LOEUF score, 1.03, which puts it in group 4 of 6, group 1 being the genes least tolerant of losing a copy. Missense variants: 433 observed, 496.73 expected, observed/expected ratio (o/e) 0.87, 90% interval 0.81 to 0.94. Synonymous variants: 161 observed, 193.91 expected, observed/expected ratio (o/e) 0.83, 90% interval 0.73 to 0.95.
Homologues: Orthologues: chimpanzee SIRT2 (100% identical), macaque SIRT2 (99% identical), mouse Sirt2 (88% identical), pig SIRT2 (86% identical), dog SIRT2 (85% identical), rat Sirt2 (83% identical), guinea pig SIRT2 (79% identical), rabbit SIRT2 (78% identical), tropical clawed frog sirt2 (66% identical), zebrafish sirt2 (63% identical), Drosophila melanogaster Sirt2 (46% identical). Paralogues in human: SIRT3 (39% identical), SIRT1 (36% identical), SIRT5 (18% identical), SIRT4 (17% identical), SIRT7 (17% identical), SIRT6 (15% identical).
Diseases named in the same sentence as SIRT2 in open-access papers:
SIRT2 is named in the same sentence as 259 diseases in open-access papers, as found by Europe PMC text mining. Sharing a sentence is not in itself a finding about the gene and the disease. The quoted sentences say what the papers report.
Parkinson disease (64 papers, 2008 to 2025). A progressive degenerative disorder of the central nervous system characterized by loss of dopamine producing neurons in the substantia nigra and the presence of Lewy bodies in the substantia nigra and locus coeruleus. "Aberrant activity of SIRT2 has been associated with neurodegenerative diseases, particularly Parkinson’s disease." (PMID 39338285, 2024). "SIRT2 is implicated in the regulation of alpha-synuclein, a protein that aggregates abnormally in Parkinson’s disease." (PMID 39338285, 2024). "Abnormal SIRT2 activity is associated with diseases such as Parkinson’s, cancer, and metabolic disorders, making it an important focus for therapeutic discovery." (PMID 39338285, 2024). "SIRT1 and SIRT2 are the most abundant sirtuins in the brain, and both are highly associated with neurodegenerative diseases including AD, Parkinson's disease (PD), and Huntington's disease (HD)." (PMID 37602729, 2023). "And AK7, another SIRT2 inhibitor, ameliorated alpha-synuclein toxicity and reduced dopaminergic neuron loss in Parkinson’s disease." (PMID 37215138, 2023). "Studies demonstrated that the variant in rs2015 for SIRT2 gene was associated with susceptibility to colorectal cancer, Alzheimer's disease, and Parkinson's disease in Chinese Han population." (PMID 35224092, 2022). "miR-486-3p binds to the 3′-UTR of SIRT2, and single nucleotide polymorphisms (SNPs), such as rs2241703, in this binding site were identified in Parkinson’s disease patients." (PMID 34943825, 2021). "Another study also identified an SNP, rs2015, in the target site of miR-8061 in the 3′-UTR of SIRT2, which was shown to contribute to the risk of Parkinson’s disease." (PMID 34943825, 2021). "Recent evidence revealed that dysregulation of human SIRT2 activity is associated with the pathogenesis and prognosis of cancers, Parkinson's disease and other disorders; thus SIRT2 is a promising target for potential therapeutic intervention." (PMID 35521274, 2020). "For instance, an SNP locus (rs2241703) in the 3’UTR of the SIRT2 gene, which disrupted the binding site of miR-486-3p, was associated with the risk of Parkinson’s disease." (PMID 32438712, 2020). "To conclude, our results are encouraging with respect to developing inhibitors of SIRT2, which are safe in terms of susceptibility to infections, for treating metabolic and neurodegenerative diseases, such as Parkinson’s disease and Huntington’s disease." (PMID 28894448, 2017). "Sirtuin 2 was previously shown to modulate proteotoxicity associated with age-associated neurodegenerative disorders such as Alzheimer and Parkinson disease (PD)." (PMID 28257421, 2017). "The mammalian SIRT2 has been implicated in Parkinson's disease (PD) where studies suggest SIRT2 promotes neurodegeneration." (PMID 28634568, 2017). "Our finding that modulating the SIRT2 levels causes changes in the nuclear envelope morphology that are also observed in Parkinson's disease provides an additional insight into the mechanism of SIRT2-mediated neurodegeneration." (PMID 27875273, 2016). "The aberrant nuclear morphology caused by SIRT2 depletion or overexpression is reminiscent of the deformed nuclei that were observed in late-passage neural stem cells or brain tissue from Parkinson's disease patients." (PMID 27875273, 2016). "Previous studies have corroborated that specific SIRT2 single-nucleotide polymorphisms (SNPs) correlate to the risk of a number of neurodegenerative diseases, like Alzheimer’s disease (AD) and Parkinson’s disease (PD) under certain conditions." (PMID 34108853, 2021). "SIRT2 levels have been associated with the pathogenesis of Parkinson’s disease." (PMID 28445509, 2017). "In contrast to Sirt1, Sirt2 may contribute to neurodegeneration given its high expression levels in neurodegenerative disorders, including AD and Parkinson’s disease (PD), and the Sirt2 single-nucleotide polymorphism rs10410544 has been reported to increase the risk of AD." (PMID 35701718, 2022).
Parkinson disease (continued). "Selective and potent inhibitors of the NAD+-dependent deacetylase Sirt2 represent a valuable epigenetic strategy for the treatment of currently incurable diseases such as Parkinson’s disease, Huntington’s disease, Alzheimer’s disease, and multiple sclerosis." (PMID 41155149, 2025). "Among the 7 sirtuin proteins, the beneficial effect of SIRT2 inhibition in AD, Parkinson’s Disease and Huntington’s Disease indicates its potential role in neurodegeneration and disease pathogenesis." (PMID 39815261, 2025). "In the same field, a recent study reported that treatment with ferulic acid (FA) causes the blocking of oxidative stress through ERK1/2-mediated activation of the Nrf2 and SIRT2 inhibition in an in vitro model of Parkinson’s disease." (PMID 38396635, 2024). "ICL-SIRT078 treatment of a rat dopaminergic neural cell line also attenuated loss of cell viability in induced Parkinson’s disease cell death, consistent with prior reports of the benefits of Sirt2 inhibition in Parkinson’s disease." (PMID 38474697, 2024). "In particular, the concentration of serum SIRT2 has been found to potentially differentiate Parkinson’s disease from Parkinsonism syndromes." (PMID 37684620, 2023). "In particular, SIRT2 has been shown as a potential blood biomarker to differentiate Parkinson’s disease from Parkinsonian Syndromes." (PMID 37684620, 2023). "As such, AK-1 and other SIRT2 inhibitors are being tested in in vitro and in vivo models of Parkinson and Alzheimer disease." (PMID 36719240, 2023). "Researchers discovered that elevated serum SIRT2 protein was correlated with higher α-Syn Parkinson’s disease patients." (PMID 37684620, 2023). "Meanwhile, CDK5 mediates nuclear translocation Sirtuin 2 (SIRT2) by directly phosphorylating SIRT2 residues, thereby promoting the death of dopaminergic neurons in a mouse model of Parkinson's disease." (PMID 36964998, 2023). "On the contrary, although SIRT2 can directly bind with and deacetylate FOXO3a upon caloric restriction and oxidative stress, significant overexpression of SIRT2 was found in Parkinson’s patients compared to normal group." (PMID 35625059, 2022). "Overall, the miR-212-5p–SIRT2 axis promotes cancer cell invasion, migration, and proliferation but was shown to prevent dopaminergic neuronal cell death in a Parkinson’s disease model." (PMID 34943825, 2021). "Another compound showing SIRT2 inhibition was found to have protective effects against neuronal cell death in a Parkinson’s disease model." (PMID 34943825, 2021). "The repression of SIRT2 is well established to ameliorate neurological deficits in in vivo models of Alzheimer’s and Parkinson’s diseases." (PMID 34943825, 2021). "The inhibition of SIRT2 expression or deacetylase activity was shown to rescue a‐synuclein toxicity in a model of Parkinson's disease." (PMID 34053152, 2021). "Targeting the expression or deacetylation activity of SIRT2 has been shown to benefit in several neurodegenerative diseases such as Parkinson's disease, Huntington's disease, and amyotrophic lateral sclerosis (ALS), but not shown benefit in CMT." (PMID 34053152, 2021). "Another SIRT2 inhibitor, AK-7, ameliorated α-synuclein toxicity and showed neuroprotective effects in models of Parkinson’s disease." (PMID 34943825, 2021). "The relationships between SIRT2 and Parkinson’s and Alzheimer’s diseases are becoming clearer, and SIRT2 inhibition is a crucial therapeutic strategy for these diseases." (PMID 34943825, 2021). "In neurodegeneration models, AGK2, a sirtuin inhibitor with higher selectivity for SIRT2 (IC50 for SIRT1 >50 μM and SIRT2 23.5 μM, respectively) showed protection from alpha-synuclein toxicity in Parkinson’s disease model." (PMID 31973227, 2020).